Y_RNA (Y RNA )
Gene: Miscellaneous RNA gene on chromosome X (12,149,126 to 12,149,238, forward strand). Ensembl gene ENSG00000206795.
Homologues: Orthologues: chimpanzee Y_RNA (97% identical), macaque Y_RNA (95% identical). Paralogues in human: Y_RNA (88% identical), RNY1 (88% identical), Y_RNA (87% identical), Y_RNA (86% identical), Y_RNA (85% identical), Y_RNA (84% identical), RNY1P8 (83% identical), Y_RNA (83% identical), RNY1P11 (82% identical), Y_RNA (82% identical), RNY1P10 (81% identical), Y_RNA (81% identical), and 95 more.